C4orf36 (chromosome 4 open reading frame 36)
Synonyms: MGC26744
Tractability: No criterion of Open Targets' tractability assessment is met for any kind of drug.
Gene: Protein-coding gene on chromosome 4 (86,876,205 to 86,892,813, reverse strand). Ensembl gene ENSG00000163633.
Subcellular location (Human Protein Atlas): Cytosol; Focal adhesion sites; Vesicles
Genetic constraint (gnomAD): Loss-of-function variants: 11 observed, 12.57 expected, observed/expected ratio (o/e) 0.88, 90% interval 0.55 to 1.45. The upper end of that interval is the gene's LOEUF score, 1.45, which puts it in group 5 of 6, group 1 being the genes least tolerant of losing a copy. Missense variants: 137 observed, 141.43 expected, observed/expected ratio (o/e) 0.97, 90% interval 0.84 to 1.12. Synonymous variants: 54 observed, 54.67 expected, observed/expected ratio (o/e) 0.99, 90% interval 0.79 to 1.24.
Homologues: Orthologues: chimpanzee C4H4orf36 (99% identical), macaque C5H4orf36 (93% identical), rabbit C4orf36 (78% identical), dog C4orf36 (74% identical), guinea pig C4orf36 (66% identical), pig C4orf36 (66% identical), mouse 1700016H13Rik (63% identical), rat C14h4orf36 (59% identical).
Diseases named in the same sentence as C4orf36 in open-access papers:
C4orf36 is named in the same sentence as 1 disease in open-access papers, as found by Europe PMC text mining. Sharing a sentence is not in itself a finding about the gene and the disease. The quoted sentences say what the papers report.
liver disease (1 paper, 2025). "Future functional studies are required to elucidate C4orf36’s biological significance and mechanisms in liver disease." (PMID 40823550, 2025).